THBS1 (thrombospondin 1)
Diseases named in the same sentence as THBS1 in open-access papers (continued):
Sharing a sentence is not in itself a finding about the gene and the disease.
abdominal aortic aneurysm (3 papers, 2020 to 2023). Enlargement and ballooning of the vessel that supplies arterial blood to the abdomen, pelvis and legs. "Despite exerting anti-inflammatory functions, thrombospondin-1 is associated with vascular inflammation properties as well, as evidenced by a THBS1 knockout mouse model of chemically induced abdominal aortic aneurysm." (PMID 37600779, 2023). "Recent investigations strongly suggest that Thbs1 contributes to the development of abdominal aortic aneurysm (AAA) through acceleration of vascular inflammation." (PMID 35432454, 2022). "Moreover, THBS1 contributes to vascular inflammation in the abdominal aortic aneurysm through activation of TGF-β1, and THBS1 mediates endothelial cell apoptosis by activating caspase." (PMID 33414684, 2020).
adenoma (3 papers, 2016 to 2025). A neoplasm arising from the epithelium. "Extensive co-expression of Thbs1 and Lgr5 in adenomas is accompanied by the presence of large tumour regions rich in cells presenting nuclear YAP, which were not visible in invasive adenocarcinomas." (PMID 35543624, 2022). "Supporting our results in mouse adenomas, the analysis of human tumours at different stages revealed that Thbs1 is highly expressed in Lgr5+ cells only in early-stage adenomas but not in advanced carcinomas." (PMID 35543624, 2022). "This metabolic profile suggests that the protective role of thrombospondin 1 to decrease adenoma formation in ApcMin/+ mice results in part from improved mitochondrial function." (PMID 27239962, 2016). "ApcMin/+:Thbs1−/− mice that were fed a low-fat diet had a 40% (P<0.03) increase in adenoma formation in their small intestine and a 52% (P<0.02) increase in the large intestine when compared with ApcMin/+ mice fed the same diet." (PMID 27239962, 2016). "Based on the consistency of their expression changes in the adenoma groups across both cohorts and their differential expression between inflammatory polyps and adenomas, we selected APOA4 and FLNA for further investigation, while excluding FERMT3 and THBS1." (PMID 41367384, 2025).
Alzheimer disease (3 papers, 2018 to 2025). A progressive, neurodegenerative disease characterized by loss of function and death of nerve cells in several areas of the brain leading to loss of cognitive function such as memory and language. "Thrombospondin-1 decreases in humans and animal models of Alzheimer’s disease in an autophagy-dependent manner, and β-amyloid application decreases thrombospondin-1 secretion." (PMID 36232390, 2022).
Amoebiasis (3 papers, 2015 to 2023). "Most of the upregulated DEPs, except Thrombospondin 1, Agrin, and Syndecan-1, involved in the ECM-receptor interaction pathway were also enriched in the amoebiasis pathway." (PMID 38069077, 2023).
clear cell renal carcinoma (3 papers, 2020 to 2024). A malignant epithelial neoplasm of the kidney characterized by the presence of lipid-containing clear cells within a vascular network. "In vitro, THBS1 inhibited the migration of clear cell renal carcinoma cells." (PMID 34268116, 2021). "THBS1, THBS2 and THBS5 proteins exhibited relatively high expression in six cancer types compared to normal samples, except for THBS5 in clear cell renal cell carcinoma (CCRCC), while THBS3 and THBS4 proteins showed lower levels in colon adenocarcinoma (COAD) and HNSC." (PMID 39732719, 2024).
diabetic retinopathy (3 papers, 2022 to 2025). "THBS1, an anti-angiogenic factor, is known to regulate extracellular matrix (ECM) homeostasis and suppresses retinal neovascularization in models of diabetic retinopathy." (PMID 40001591, 2025).
fragile X syndrome (3 papers, 2016 to 2024). A genetic syndrome caused by mutations in the FMR1 gene which is responsible for the expression of the fragile X mental retardation 1 protein. "These genes include ATP Binding Cassette Subfamily B Member 1 (ABCB1) and Thrombospondin-1 (THBS1), as well as the fragile X messenger ribonucleoprotein 1 (FMR1) gene in Fragile X Syndrome to induce transcriptional repression." (PMID 39108836, 2024).
head and neck squamous cell carcinoma (3 papers, 2021 to 2024). A squamous cell carcinoma that arises from any of the following anatomic sites: lip and oral cavity, nasal cavity, paranasal sinuses, pharynx, larynx, and salivary glands. "Moreover, THBS1 has been shown to enhance cancer cell invasion in head and neck squamous cell carcinoma (SCC) and esophageal SCC59,60, while inhibiting tumor vascularization and progression in oral and cutaneous SCC61." (PMID 39468077, 2024). "In patients with head and neck squamous cell carcinoma (HNSCC), upregulation of CALM1, CYCS, THBS1, MYC, GATA6, and SPRED3 was strongly associated with a poor prognosis." (PMID 36239104, 2022).
Infertility (3 papers, 2009 to 2026). "A more complete understanding of THBS1 actions may ultimately enhance treatments for infertility and point to new targets for contraceptive development." (PMID 31787928, 2019). "In order to verify whether this observation could have been biased by the lack of control for several possible confounders, the mean thrombospondin-1 serum levels was adjusted with respect to gravidity, length of menses, infertility and BMI in a univariate general linear model." (PMID 19917115, 2009).
intrahepatic cholangiocarcinoma (3 papers, 2022 to 2025). A carcinoma that arises from the intrahepatic bile duct epithelium in any site of the intrahepatic biliary tree. "Together with THBS1 and SERPINF1, it has also been shown to inhibit angiogenesis in patients with intrahepatic cholangiocarcinoma." (PMID 35163504, 2022).
Kaposi's sarcoma (3 papers, 2007 to 2012). A malignant neoplasm characterized by a vascular proliferation which usually contains blunt endothelial cells. "Another example is protein thrombospondin 1, which is down regulated by Kaposi sarcoma-associated herpesvirus-encoded miRNAs." (PMID 23155403, 2012). "There are only very limited data about the status of THBS1 in sarcomas, a decreased expression having been reported in Kaposi sarcoma or Ewing sarcoma." (PMID 22383169, 2012). "THBS1 has previously been reported to be down-regulated in Kaposi sarcoma lesions and has known activity as a strong tumor suppressor and anti-angiogenic factor, exerting its anti-angiogenic effect in part by activating the latent form of TGF-β." (PMID 17500590, 2007).
laryngeal carcinoma (3 papers, 2014 to 2023). Carcinoma that arises from the laryngeal epithelium. "In summary, knockdown of THBS1 inhibited laryngeal cancer cell migration, invasion, and proliferation, suggesting that THBS1 can promote the development of laryngeal cancer cells." (PMID 36335208, 2022). "We found that cell invasion, migration, and proliferation were significantly diminished after the knockdown of THBS1 in laryngeal cancer cells." (PMID 36335208, 2022). "It was also found that THBS1, a high-risk and prognosis-related gene, may regulate the occurrence and development of laryngeal cancer through fatty acid metabolism, which has further helped us to explore the role of fatty acid metabolism genes in laryngeal cancer." (PMID 36335208, 2022). "Furthermore, we investigated the cellular function of THBS1 by constructing a THBS1 knockdown stable cell line for laryngeal carcinoma." (PMID 36335208, 2022). "We also found that THBS1 could promote the migration, invasion and proliferation of laryngeal cancer cells by constructing THBS1 knockout cell lines." (PMID 36335208, 2022). "We speculate that THBS1 may regulate the occurrence and development of laryngeal cancer through fatty acid metabolism, but we still need to conduct in-depth mechanism research in the future." (PMID 36335208, 2022). "We constructed THBS1 knockdown cell stable transfer lines with two cell lines, LCC and TU686, from a laryngeal carcinoma and validated them using PCR." (PMID 36335208, 2022).
leiomyoma (3 papers, 2007 to 2014). A well-circumscribed benign smooth muscle neoplasm characterized by the presence of spindle cells with cigar-shaped nuclei, interlacing fascicles, and a whorled pattern. "Other groups found that leiomyomas express THBS1 more frequently than leiomyosarcomas." (PMID 24398114, 2014). "In contrast, the expression of EGR3, ECM2, THBS1, GAS1 and FBLN5 in scars and RUNX3 and COL18 expression in peritoneal adhesions was higher as compared to leiomyomas." (PMID 17718906, 2007). "PTSMT have an increased MYC expression and low levels of THBS1 but no up-regulation of the miR 17~92 cluster, including miR-19a (in PTSMT mean relative expression level 0.02 versus 0.03 in leiomyomas) and miR-19b (mean 1.63 in PTSMT versus 2.23 in leiomyomas)." (PMID 24398114, 2014).
Lewis lung carcinoma (3 papers, 2016 to 2024). "Conversely, treatment with the CD47 ligand thrombospondin-1 was recently reported to inhibit proliferation, sphere formation, and expression of stem cell transcription factors in Lewis lung carcinoma cells, and CD47 shRNA knockdown blocked this activity." (PMID 26840086, 2016).
liver failure (3 papers, 2024 to 2025). A liver disease characterized by the liver losing or has lost all of its function. "Extended liver resection carries the risk of post-surgery liver failure involving thrombospondin-1-mediated aggravation of hepatic epithelial plasticity and function." (PMID 38534373, 2024). "Through comprehensive analyses with various methods, external cohort validation and development of two liver failure animal models, we finally characterized THBS1 as an important target and potential novel biomarker involved in ACLF pathogenesis." (PMID 38439091, 2024). "Overall, THBS1 may further aggravate liver failure by promoting hepatic inflammatory responses and inducing hepatocyte apoptosis." (PMID 38439091, 2024). "These outcomes strengthened our hypothesis that THBS1 expression is correlated with inflammation, as knocking out THBS1 significantly attenuates the inflammatory responses following liver failure." (PMID 38439091, 2024). "In the progression of ACLF, elevated THBS1 levels could contribute to liver dysfunction, intensifying hepatic damage and cellular death through the activation of key pathways, such as TGF-β1 and NF-κB, thereby precipitating liver failure." (PMID 38439091, 2024).
multiple myeloma (3 papers, 2022 to 2025). "Meanwhile, THBS1/CD47 interactions also activate NF-κB–RANK ligand signaling to increase malignancy and metastasis in myeloma cells." (PMID 40988744, 2025).
myelofibrosis (3 papers, 2021 to 2025). A partial or complete replacement of the bone marrow stroma by fibrous tissue. "Thrombospondins 1 (THBS1) is an extracellular matrix protein that affects diverse cellular activities and has been confirmed as a therapeutic biomarker for primary myelofibrosis." (PMID 38267974, 2024). "Some studies suggest that THBS1 to be a biomarker for monitoring a primary myelofibrosis targeted therapy." (PMID 33912465, 2021).
nonalcoholic steatohepatitis (3 papers, 2024 to 2025). "THBS1 impacts on liver metabolism towards lipid storage, thus supporting the pathogenesis of MASH (Metabolic Dysfunction-Associated SteatoHepatitis) in rodents and humans." (PMID 38534373, 2024).
pancreatic adenocarcinoma (3 papers, 2019 to 2025). "In the invasion of human pancreatic adenocarcinomas, THBS1 was implicated in regulating matrix remodeling and played pivotal role in cancer cell growth and metastasis." (PMID 31412643, 2019). "Hence, stromal THBS1 immunoreactivity and expression was considered as a prognostic marker and a new indicator of invasiveness in patients with pancreatic adenocarcinomas." (PMID 31412643, 2019).
pneumonia (3 papers, 2012 to 2024). An acute, acute and chronic, or chronic inflammation focally or diffusely affecting the lung parenchyma, caused by an infection in one or both of the lungs (by bacteria, viruses, fungi, or mycoplasma.). "THBS1-deficient mice have spontaneous pneumonia that leads to pulmonary hemorrhage, macrophage infiltrations and permanent damage to the lungs, which suggests that this protein is important for maintaining normal pulmonary homeostasis by limiting the extent and/or duration of inflammation." (PMID 23006927, 2012). "Among the 27 focal adhesion-related dysregulated proteins (18 up-regulated and 9 down-regulated), thrombospondin-1 (THBS1) and caveolin-1 (CAV1) have been reported to be associated with pneumonia." (PMID 36387401, 2022). "Furthermore, silencing of THBS1 can inhibit the activation of the NLRP3 inflammasome, reducing the levels of inflammatory cytokines, thereby reducing pneumonia caused by cytokine storms." (PMID 38424541, 2024).
polycystic ovary syndrome (3 papers, 2013 to 2023). A disorder that manifests as multiple cysts on the ovaries. "Thbs4 is abundant in normal ovary and related to the polycystic ovary syndrome-associated gene Thbs1." (PMID 38031019, 2023). "Interestingly, metformin reportedly increases the levels of anti-angiogenic thrombospondin-1 (TSP1) in the serum of women with polycystic ovarian syndrome and thereby inhibited angiogenesis." (PMID 31698699, 2019). "In the recurrence subnetworks, DCN, THBS1, and THBS2 are members of the signaling KEGG pathway, and FBN1 controls the bioactivity of TGFs and relates to polycystic ovary syndrome." (PMID 23555212, 2013).
small cell lung carcinoma (3 papers, 2016 to 2024). Small cell lung cancer (SCLC) is a highly aggressive malignant neoplasm, accounting for 10-15% of lung cancer cases, characterized byrapid growth, and early metastasis. "As an extracellular matrix (ECM) component, THBS1 has been reported to inhibit cell proliferation in small-cell lung carcinoma cells." (PMID 38339060, 2024). "The mRNA level of THBS1 was significantly underexpressed in small cell lung cancer (a fold change of -5.923)." (PMID 27513329, 2016).
triple-negative breast carcinoma (3 papers, 2021 to 2024). An invasive breast carcinoma which is negative for expression of estrogen receptor (ER), progesterone receptor (PR), and human epidermal growth factor receptor 2 (HER2). "Blocking Thbs1 with a genetic approach in triple-negative breast cancer (TNBC) was shown to increase CD8 T cells infiltration/proliferation and improve response to αPD-L1 immunotherapy in mice." (PMID 38499573, 2024). "But THBS1 knockdown indirectly increased CD8+ TILs by increasing tumor vascularization in triple-negative breast cancer." (PMID 37853469, 2023).
Ureteral obstruction (3 papers, 2018 to 2024). Obstruction of the flow of urine through the ureter. "Similar results were also found in high-fat diet-fed THBS1-deficient mice, as well as ureteric obstruction model, which showed blockade of inflammatory lesions and lower renal interstitial inflammation." (PMID 38439091, 2024). "THBS1 is also considered a cytokine that can promote the transcription of transforming growth factor-β (TGF-β) mRNA in the renal interstitial fibrosis of rats with a unilateral ureteral obstruction." (PMID 29950996, 2018).
acute liver failure (2 papers, 2021 to 2024). Rapid deterioration of liver function causing encephalopathy and coagulopathy. "Since liver dysfunction involving THBS1 improves with MSC treatment in various animal models, it seems feasible to also modulate THBS1 in humans to impede post-surgery acute liver failure." (PMID 38534373, 2024). "QCLGF may alleviating intestinal flora disorder, regulating galactose metabolism and downregulating the expression of THBS1 to alleviate D-GalN induced acute liver failure." (PMID 35127552, 2021).
age-related macular degeneration (2 papers, 2016 to 2020). Age-related loss of vision in the central portion of the retina (macula), secondary to retinal degeneration. "Impaired expression of thrombospondin-1 in Bruch's membrane and choroidal vessels was shown in the rodent eyes with age-related macular degeneration." (PMID 26881021, 2016).
Bladder Urothelial Carcinoma (2 papers, 2023 to 2024). "In bladder urothelial carcinoma (BLCA), THBS1 counteracted the tumor-associated behavior of miR-19a-3p in BLCA cells." (PMID 38183097, 2024).
brain cancer (2 papers, 2024 to 2025). A primary or metastatic malignant neoplasm affecting the brain. "Compared to normal tissues, THBS1 and THBS2 showed higher expression in brain cancers and PAAD, but lower expression in cervical squamous cell carcinoma and endocervical adenocarcinoma (CESC), OV, uterine corpus endometrial carcinoma (UCEC) and uterine carcinosarcoma (UCS)." (PMID 39732719, 2024).
chronic liver failure (2 papers, 2024 to 2025). Liver failure that develops slowly and gradually for some time, possibly for years, often as the result of cirrhosis, or malnutrition. "Thrombospondin-1 (THBS1) is a secreted glycoprotein found mainly in blood and extracellular matrix (ECM), occupying an important position in several biological processes (BP) of RILI, including promoting hepatic inflammatory response, mediating acute and chronic liver failure, and fibrin deposition." (PMID 41394148, 2025).
dementia (2 papers, 2023). Loss of intellectual abilities interfering with an individual's social and occupational functions. "The findings suggest that WDR43 and THBS1 are potential targets for preventing and treating CV-induced dementia in the elderly." (PMID 37122373, 2023).
dengue (2 papers, 2016 to 2025). "Elevated mRNA levels of MIF and decreased mRNA level of thrombospondin-1 were observed in dengue patients (including dengue fever and dengue hemorrhagic fever)." (PMID 27549428, 2016). "Thrombospondin-1 (THBS1), released from α-granules of activated platelets, points to aggregation and consumption, correlating with thrombocytopenia, bleeding, plasma leakage, and organ failure in severe dengue, peaking critically (days 3–4 post-infection) and resolving post-convalescence." (PMID 41583452, 2025). "The identified DEPs, such as STXBP5, THBS1, and PRG2, have potential as biomarkers for predicting severe dengue outcomes." (PMID 41583452, 2025). "Despite the small sample size (n = 18) limiting generalizability, this approach enabled deep profiling in a resource-limited setting and revealed candidate biomarkers (e.g., thrombospondin-1 and STXBP5) and pathways (e.g., complement and TGF-β) for severe dengue." (PMID 41583452, 2025).
depression (2 papers, 2024). "Additionally, there exist a multitude of significant genes that vary between sexes and are linked to depression, like ORM1, ORM2, RNF32, SLC25A5, Thbs1, and Cadps2 etc., manifesting sex-specific impacts on depression risk." (PMID 38903903, 2024).
dermatitis (2 papers, 2011 to 2016). An inflammatory process affecting the skin. "Several other transcriptional changes in SKO mice parallel other models of wound healing and dermatitis including elevated expression of tenascin C (Tnc), osteopontin (Spp1), thrombospondin-1 (Thbs1) and Socs3." (PMID 21573029, 2011).
diabetic cardiomyopathy (2 papers, 2016 to 2020). Diabetic cardiomyopathy is a disorder of the heart muscle in people with diabetes. "Others have shown that THBS1 peptide antagonist prevented the progression of cardiac fibrosis and improved cardiac function by reducing TGF-β activity in a rat model of diabetic cardiomyopathy." (PMID 27635260, 2016). "It is now clear that THBS1 is one of the most important physiological activators of TGF-β1, and research has shown that the THBS1-activated TGF-β1/Smad2/3 signaling pathway may play an important role in the development of myocardial interstitial fibrosis in diabetic cardiomyopathy." (PMID 33414684, 2020).